ERBB2 (erb-b2 receptor tyrosine kinase 2)
Diseases named in the same sentence as ERBB2 in open-access papers (continued):
Sharing a sentence is not in itself a finding about the gene and the disease.
breast cancer (continued). "Genetic profiling has revealed several subclasses of breast cancer based on hormone receptor (ER and PR) and HER2 (ERBB2) status: luminal ER-positive and PR-positive, which is further subdivided into luminal A and B; HER2-positive; and triple-negative breast cancer (TNBC; ER-ve PR-ve HER2-ve)." (PMID 38920970, 2024). "Similarly, “ERBB2 signaling” and “ERBB2-ERBB3 signaling” pathways were identified from the boosted gene set, where HER2 and HER3 heterodimer signaling is vital for HER2-positive breast cancer by enhancing cell survival and proliferation." (PMID 39519370, 2024). "Early-stage tumors that are estrogen receptor (ER) positive and ERBB2 (formerly HER2/neu) (OMIM 164870) negative comprise 70% of breast cancer diagnoses, and a survival disparity according to race and ethnicity among patients with this disease subtype is well documented." (PMID 38568689, 2024). "The 21-gene Oncotype DX Breast Recurrence Score may inform decisions on adjuvant chemotherapy in postmenopausal luminal ERBB2-negative breast cancer with 1 to 3 metastatic ALNs without CALND." (PMID 39320882, 2024). "Overactivation of ErbB2 signaling leads to activation of the transcription factor MZF1 which in turn increases the expression of the lysosomal cholesterol transporter NPC1 and activates macropinocytosis, increasing the macropinocytotic uptake of extracellular cholesterol in breast cancer cells." (PMID 39243069, 2024). "Is fulvestrant, alone or in combination with the aromatase inhibitor anastrozole, superior to anastrozole alone as neoadjuvant endocrine therapy (NET) in postmenopausal women with estrogen receptor (ER)–rich/ERBB2-negative breast cancer, in terms of endocrine-sensitive disease rate (ESDR)?" (PMID 38236590, 2024). "Additionally, certain genetic mutations, like the V777L ERBB2 mutation and MutL deficiency—related to mismatch repair system changes—suggest potential responsiveness to anti-HER2 therapies, even in HER2-negative breast cancers." (PMID 38398191, 2024). "The RNA expression values of the ERBB2 gene in 30 breast cancer cell line panels demonstrated that SKBR3 expresses 3046 TPM (transcripts per million), BT474 expresses 2153 TPM, and MDA-MB-453 expresses 446 TPM, making SKBR3 more pronounced in expressing the ERBB2/HER2 gene than the other cell lines." (PMID 39857607, 2024). "The combination regimen of T-DM1/T-DXd and tucatinib for advanced breast cancer progression with prior taxane and trastuzumab showed acceptable toxicity and preliminary anti-tumor activity in patients with ERBB2/HER2-positive metastatic breast cancer with and without brain metastases." (PMID 38178200, 2024). "The aim of this study was to explore the influence of conditioned medium, derived from SKBR-3 cultures (a commonly used ERBB2+ human breast cancer cell line) and MCF10-A (a non-tumorigenic human mammary cell line), on both the electrophysiological activity and morphology of neural networks." (PMID 38638322, 2024). "This study aimed to analyze whether younger patients had a worse prognosis for late DR in a group of patients with ER-positive, ERBB2-negative breast cancer who were recurrence-free within 5 years after surgery." (PMID 39509133, 2024). "Finally, we examined ERBB2 levels with and without USP22 depletion in two HER2-positive human breast cancer cell lines, SKBR3 and HCC1954, and again saw no impact on ERBB2 protein levels upon USP22 loss." (PMID 38236941, 2024). "Notably, while NCAPH transgenic mice developed distinct histopathological types of breast cancer, the MMTV‐NCAPHErBb2 double‐transgenic mice developed only infiltrating ductal adenocarcinomas, suggesting that the ErbB2 oncogene exerts a dominant effect on the tumour phenotype." (PMID 38344872, 2024).
breast cancer (continued). "Unlike other breast cancer subtypes, such as triple‐negative and HER2‐enriched breast cancer, which commonly relapse within the first few years of follow‐up, ER+/ERBB2‐ invasive breast cancer often presents with a late recurrence, manifesting 5–10 years or longer after primary treatment." (PMID 39031010, 2024). "It is unclear whether breast cancer (BC) with low ERBB2 expression (ERBB2-low) is a distinct clinical, pathological, and epidemiological entity from BC classified as no ERBB2 expression (ERBB2-negative)." (PMID 38517439, 2024). "Compared with non-Hispanic White patients, of whom 66.1% had ERBB2-low breast cancer, Native American patients had a higher proportion of ERBB2-low disease (2270 [70.0%]), while the proportions were lower in non-Hispanic Black (62.8%) and Hispanic (61.0%) patients." (PMID 36821125, 2023). "Consistent with the SANDPIPER cohort, a similar proportion of clonal multiple PIK3CAmut [405 of 520 (77.9%)] was observed in the subgroup of breast cancer tissue samples that were ERBB2 non-amplified and biopsied from a metastatic site of disease, which more closely resembles the trial population." (PMID 37101291, 2023). "To confirm the co-amplification of ERBB2 and NFIB overexpression and to support the clinicopathological significance of this co-amplification in breast carcinogenesis, we collected a panel of breast cancer cell lines for western blotting analysis of the expression of NFIB." (PMID 37604829, 2023). "Her2 (human epidermal growth factor receptor 2), a tyrosine kinase receptor encoded by the ERBB2 gene, has long been known to be a negative prognostic factor for breast cancer patients." (PMID 36969021, 2023). "Women aged 40 years or older with invasive cT1-2 N0-1 M0 triple-negative or human epidermal growth factor receptor 2 (ERBB2)–positive breast cancer with no pathologic evidence of residual disease following standard NST enrolled from March 6, 2017, to November 9, 2021." (PMID 37707811, 2023). "This trial was designed to determine whether the EP regimen is noninferior to the standard EC-P regimen in both efficacy and safety for ERBB2-negative breast cancer." (PMID 36826820, 2023). "In our study, amplification of chromosome 17, in which ERBB2 is located, was very common in HER2-positive tumors, which established the unique biological property of HER2-positive breast cancer and no particular CNVs enriched in HER2-low breast cancer were identified." (PMID 37264417, 2023). "Whether in HR+ or HR− subtype, HER2-positive breast cancer was characterized by gains in 17q12 (ERBB2, CDK12, HNF1B, RAD51D), and almost no gains of 17q12 were present in the other subtypes." (PMID 37264417, 2023). "Breast cancer can be categorized as (i) ERBB2/HER2 negative/hormone receptor-positive (~70% of all cases), (ii) ERBB2 positive (15–20% incidence), and (iii) triple-negative breast cancer (which lacks all three receptors, ERBB2, estrogen receptor and progesterone receptor)." (PMID 37894581, 2023). "While the mechanistic link between miR-198 and FUT8 has not yet been investigated, it has been shown that circular ERBB2 RNA (circ-ERBB2) promotes breast cancer metastatic process, cellular invasion, and proliferation by competing with miR-198 and miR-136-5p as an endogenous RNA sponge." (PMID 36980181, 2023). "Patients with hormone receptor (HR)–positive and human epidermal growth factor receptor 2 (ERBB2, formerly HER2)–negative breast cancer had a higher risk for overall death in the CBC group (hazard ratio, 1.882; 95% CI, 1.143-3.098) compared with the no-CBC group." (PMID 37707815, 2023). "The findings of this study suggest that treatment response and long-term outcomes may be similar in ERBB2-low and ERBB2-negative cancers and do not support the classification of ERBB2-low breast cancer as a unique disease entity." (PMID 36821125, 2023).
breast cancer (continued). "Overall, most patients were married (2834 patients [63.8%]), privately insured (2650 patients [59.4%]), and had stage I disease (2814 patients [63.1%]), HR-positive/ERBB2-negative breast cancers (2753 patients [61.7%]), and no comorbidities (3520 patients [78.9%])." (PMID 37200034, 2023). "Breast cancer is a heterogeneous disorder characterized by the expressions of different receptors, like the estrogen receptor (ER), progesterone receptor (PR), and human epidermal growth factor receptor 2 (HER2, or receptor tyrosine kinase erbB2 (ERBB2)), as well as the proliferation marker Ki-67." (PMID 37626841, 2023). "No PIK3CA, BRCA1, or ERBB2 alterations were identified in the breast carcinoma cases." (PMID 36125633, 2023). "Overall, our data suggest that ERBB2/ERBB3 plays an oncogenic role in basal-like/triple-negative breast cancer patients, suggesting its neutralization as a therapeutic strategy for these breast cancer subtypes, which today have very limited treatment opportunities." (PMID 35406375, 2022). "Breast cancer can be classified into three subtypes, depending on the presence of molecular markers: hormone receptor positive/human epidermal growth factor receptor-2 gene (ERBB2) negative, ERBB2 positive, and triple-negative." (PMID 35878198, 2022). "Breast cancers are classified, inter alia, based on the expression of receptors such as estrogen receptor α (ERα; often referred to as ER), progesterone receptor (PR), and human epidermal growth factor receptor (EGFR; also known as ErbB2/HER2) with tyrosine kinase activity." (PMID 35954312, 2022). "However, recent study demonstrated that both breast-specific Akt1 and Akt2 deletion impaired breast cancer development driven by ErbB2 overexpression, but breast cancer metastasis was not affected by breast-specific Akt1 deletion." (PMID 36180910, 2022). "Most breast cancers express specific hormone receptors (HRs) for estrogen (estrogen receptor α, ERα) and progesterone (progesterone receptor, PR), and some cancers exhibit human epidermal growth factor receptor 2 (HER2)/erb-b2 receptor tyrosine kinase 2 (ERBB2) gene amplification or overexpression." (PMID 35178385, 2022). "Accordingly, breast cancers are classified as tumors expressing estrogen receptor-α (ERα/ESR1), progesterone receptor (PGR) and/or epidermal growth factor (EGF) family receptor HER2/ERBB2, which emanate from luminal epithelial progenitors and are classified as luminal-A or -B." (PMID 36171192, 2022). "Body mass index (BMI) may affect the 21-gene recurrence score (RS) in patients with ER-positive, ERBB2-negative breast cancer." (PMID 36441548, 2022). "To clarify the timing of initiation of AHT and the association with survival for HR-positive and ERBB2 (formerly HER2)-negative early breast cancer without chemotherapy, we conducted a large population-based retrospective study using data from the National Cancer Database (NCDB)." (PMID 35166783, 2022). "Cumulative incidence of BRM was higher among patients with ERBB2-positive/HR-negative breast cancer (34.7%), ERBB2-positive/HR-positive breast cancer (28.1%), and triple-negative breast cancer (21.9%) compared to those with HR-positive/ERBB2-negative breast cancer (12.1%)." (PMID 35960523, 2022). "Furthermore, TCGA database shows that patients with ERBB2 fusions in pan-cancer had a worse prognosis than those without ERBB2 fusions, as well as in breast cancer." (PMID 36276102, 2022). "In this study we used ERBB2d16/ERBB2 ratio to indicate and differentiate the expression of ERBB2d16 for the first time and found that high expression of ERBB2d16 was related to EMT and resistance to trastuzumab, which was consistent with the previous study in breast cancer." (PMID 35463314, 2022). "In this study, findings from interviews revealed that oncologists' perspectives may have implications for the largely unsuccessful deimplementation of SLNB in women 70 years and older with cT1N0 HR-positive, ERBB2-negative breast cancer." (PMID 36001314, 2022).
breast cancer (continued). "Breast cancer is categorized into five major subtypes by molecular and immunohistochemical profiling: luminal A (ER+PR+HER2−Ki67low), luminal B (ER+HER2−Ki67high or PR−), luminal B-like (ER+HER2+), ERBB2/HER2-enriched (ER−PR−HER2+), and triple negative (TN)/basal-like (ER−PR−HER2−)." (PMID 36556357, 2022). "Clinically, specific subtypes of breast cancer are defined by their histopathological appearance and expression of hormone receptors and growth factors [namely, the estrogen receptor (ER), the progesterone receptor (PR) and human epidermal growth factor receptor 2 (HER2; also known as ERBB2]." (PMID 34722507, 2021). "Thus, reproductive history affects NeuNT/Erbb2 locus amplification and the activation of specific branches of the WNT signalling pathway and ultimately drives inter-tumour heterogeneity in this murine model of human HER2 breast cancer." (PMID 34003256, 2021). "Of those diagnosed with breast cancer, 15–20% are classified as triple-negative breast cancer (TNBC), which is identified by the absence of an estrogen receptor (ER) and a progesterone receptor (PR) and does not make too much of epidermal growth factor receptor type 2 (Erbb2/HER2)." (PMID 34680349, 2021). "This secondary analysis of the Stockholm tamoxifen clinical trial examines the association of clinical breast cancer markers with 25-year survival and tamoxifen treatment benefit among postmenopausal women with lymph node–negative ER-positive/ERBB2-negative breast cancer." (PMID 34190995, 2021). "Vice versa, in breast cancer, we never detected a nuclear ErbB2 expression." (PMID 32591879, 2021). "Since DNA-level epigenetic regulation (promoter CpG island methylation) has no role in the expression of ERBB2, we hypothesized that chromatin remodeling may control ERBB2 expression in the epithelial-like and mesenchymal-like breast cancer cells." (PMID 34575017, 2021). "Breast cancer can be divided into the molecular types—luminal A, luminal B, ERBB2+, and triple negative breast cancer (TNBC)—based on different expression profiles of the estrogen receptor (ER), progesterone receptor (PR), and human epidermal growth factor receptor 2 (HER2)." (PMID 34563270, 2021). "In this study, we demonstrate that ERBB2 promotes autophagy by upregulating ATG12 as well as other autophagy-related (ATG) proteins including ULK1, FIP200, ATG5, and ATG7, leading to breast cancer treatment resistance and worse outcome to patients with ERBB2-positive breast cancer." (PMID 33801244, 2021). "This could account for our observation of a pool of CHIP and ErbB2 in the Golgi but not in the ER in stably CHIP-overexpressing ErbB2-overexpressing breast cancer cells." (PMID 34439093, 2021). "Among the 81 patients with ERBB2 amplification (ESCAT Tier IA), 15 (18.8%) were clinically HER2 negative, indicating that targeted sequencing may identify more HER2 positive breast cancers than traditional IHC/in situ hybridization assays." (PMID 33632156, 2021). "In human epidermal growth factor receptor 2‐positive breast cancer cell lines, free tRNALeu may interact with human epidermal growth factor receptor 3 (ErbB3) and binding protein (EBP1), which in turn activates the ErbB2/ErbB3 signaling pathways, and ultimately promotes cancer cell proliferation." (PMID 34048096, 2021). "Interestingly, ErbB2 activation upregulates GLS1 expression in breast cancer cells via NF-κB pathway rather than c-Myc." (PMID 34906193, 2021).
breast cancer (continued). "Triple-negative breast cancer (TNBC) comprises a subgroup of breast cancers (BC) identified by a lack of expression of the estrogen receptor (ER) and progesterone receptors (PR), and without amplification of Human Epidermal Growth Factor Receptor-2 (HER2 or ERBB2)." (PMID 34063736, 2021). "Amplifed‐ERBB2 in breast cancer activates downstream pathways including PI3K and MAPK signalling, and the mutated‐PI3Kα‐induced negative feedback may determine the success of anti‐HER2 therapy." (PMID 34842356, 2021). "ErbB1 (EGFR) and ErbB2 (HER2/Neu) drive oncogenesis in many human malignancies; ErbB2 overexpression, due to gene amplification and/or increased transcription, drives oncogenesis in up to a quarter of human breast cancer patients and specifies poor overall patient survival." (PMID 34439093, 2021). "Majority of human BRCA1-related breast cancers are negative for ERα, PR and/ or ERBB2." (PMID 34815798, 2021). "Importantly, we previously confirmed circ-ERBB2 was mainly located in the cytoplasm of HER2-positive breast cancer cells through fluorescence in situ hybridization, implying that circ-ERBB2 might function as the miRNAs sponge in HER2-positive breast cancer." (PMID 34732216, 2021). "Triple-negative breast cancer (TNBC) refers to breast carcinomas that lack the expression of hormone receptors (estrogen and progesterone receptors), and that do not express the human epidermal growth factor receptor 2 (HER2) and do not have amplification of the corresponding gene (ERBB2)." (PMID 34362334, 2021). "Overall, it suggests that shorter durations of trastuzumab may be noninferior to 1-year duration in patients with ERBB2-positive early breast cancer." (PMID 32833018, 2020). "Also, no mutations were detected for other described breast cancer‐associated genes (e.g., RAD51, RAD50, p27, ESR1/2, ERBB2, ERBB3, AKT1, CCDN1, FGFR1, MYC, and RB1) in any of the tissues or the CTC cell line." (PMID 32667137, 2020). "The work of Perou and Sorlie allowed the subdivision of breast cancers in five subtypes, distinguished by differences in their gene expression patterns with distinct clinical behaviors: basal, erb-b2 receptor tyrosine kinase 2 (ERBB/HER2), luminal A, luminal B, and normal breast-like." (PMID 32481735, 2020). "Furthermore, mouse mammary tumor models have revealed that combination therapies targeting FGF and ErbB receptors, including HER2 (ErbB2), may lead to synergistic anticancer effects." (PMID 33081025, 2020). "This signaling is ERBB2-specific and appears not to depend on ERBB2 heterodimers as in the context of the breast cancer cell line used here (expressing negligible ERBB4 levels), silencing of EGFR and ERBB3 does not impair the ERK-dependent AKT de-phosphorylation elicited by Abs." (PMID 33037285, 2020). "The ERBB2/Her2-neu -targeted therapies, such as trastuzumab, lapatinib and pertuzumab, have showed improved outcomes in patients with ERBB2/Her2-neu amplification-positive cancers, and these drugs have been approved by the FDA against ERBB2/Her2-neu-positive gastric and breast cancers." (PMID 32552660, 2020). "Using RT-PCR to examine expression levels of genes in circulating leukocytes, it was shown that TNF-alpha, IL-6, leptin and ErbB2, were significantly higher in obese individuals without a cancer diagnosis and among breast cancer patients compared to the lean group." (PMID 33597950, 2020).